DAPK1 (death associated protein kinase 1)
Diseases named in the same sentence as DAPK1 in open-access papers (continued):
Sharing a sentence is not in itself a finding about the gene and the disease.
liver cancer (continued). "In this study, we aimed to use online available microarray data from the Gene Expression Omnibus (GEO) database and an in-house liver cancer patient cohort to study the prognostic significance of DAPK1 mRNA and protein expression, respectively, in liver cancer." (PMID 28740751, 2017). "Our results suggest that the Wnt/b-catenin pathway may play a role in DAPK1 down-regulation in liver cancer." (PMID 28740751, 2017). "The mRNA expression of DAPK1 was extracted from the Gene Expression Omnibus database in three independent liver cancer datasets while protein expression of DAPK1 was detected by immunohistochemistry in our Chinese liver cancer patient cohort." (PMID 28740751, 2017). "Although extensively researched, the role of DAPK1 and its prognostic significance in liver cancer is largely unknown." (PMID 28740751, 2017). "The results suggest that DAPK1 expression was down-regulated in liver cancer." (PMID 28740751, 2017). "Our study demonstrated for the first time that both DAPK1 mRNA and protein expression levels are important prognostic markers in liver cancer, and have identified genes that may contribute to DAPK1-mediated liver carcinogenesis." (PMID 28740751, 2017). "The mechanistic insights for how DAPK1 is regulated by b-catenin in liver cancer may result in novel therapeutic approach in treatment of liver cancer." (PMID 28740751, 2017). "We have shown that DAPK1 was significantly down-regulated in the CTNNB subtype of liver cancer, and importantly in liver cancer with a b-catenin mutation, the expression of DAPK1 mRNA was significantly lower compared to those liver cancer with wild-type b-catenin." (PMID 28740751, 2017). "The results suggest that DAPK1 dysregulation may be an early event in liver cancer development." (PMID 28740751, 2017). "Low levels of DAPK1 mRNA were associated with shorter survival in a liver cancer patient cohort (n = 115; p = 0.041), while negative staining of DAPK1 protein was significantly correlated with shorter time to progression (p = 0.002) and overall survival (p = 0.02)." (PMID 28740751, 2017). "By connectivity mapping, we have identified sulpiride as one of the potential small molecules that could reverse DAPK1 and its co-regulated genes expression pattern in liver cancer, which may have potential therapeutic value in liver cancer, especially for those with reduced DAPK1 expression." (PMID 28740751, 2017). "DAPK1 expression was positively correlated with IRF2, IL7R, PCOLCE and ZBTB16, and negatively correlated with SLC16A3 in both liver cancer datasets." (PMID 28740751, 2017). "In the current study, we have also identified few genes that are co-regulated with DAPK1, especially for SLC16A3, PCOLCE and ZBTB16, since the expression of these genes were dysregulated in liver cancer." (PMID 28740751, 2017). "A high level DAPK1 expression was observed in 59% of non-tumor specimens but only 43% liver cancer specimens had similar level of DAPK1 expression (Fisher’s exact test, p = 0.001)." (PMID 28740751, 2017). "To investigate what factor may possibly lead to dysregulation of DAPK1 in liver cancer, we identified another dataset, GSE9843, which has an annotated gene signature for 74 liver cancer specimens." (PMID 28740751, 2017). "In this study, we demonstrated, for the first time that, DAPK1 was down-regulated in liver cancer compared to the non-tumor liver specimens." (PMID 28740751, 2017). "Although our findings have provided evidence on the prognostic significance of DAPK1 mRNA in liver cancer, there is still little evidence showing how DAPK1 mRNA is regulated." (PMID 28740751, 2017). "However, the mRNA expression levels of DAPK1 in liver cancer and the prognostic significance of protein and mRNA expression in Chinese liver cancer patients, to the best of our knowledge, have not been published." (PMID 28740751, 2017).
liver cancer (continued). "Indeed, majority of cirrhosis specimens also had a low level expression of DAPK1 compared to the healthy or adjacent non-tumor specimens, further supporting the hypothesis that DAPK1 down-regulation may happen early in the development of liver cancer." (PMID 28740751, 2017). "To confirm this observation, we tested DAPK1 expression in another dataset, GSE36376, which consists of 193 adjacent non-tumor specimens and 240 liver cancer specimens." (PMID 28740751, 2017).
lymph node metastasis (9 papers, 2011 to 2024). "When stratified by location, DAPK1 methylation was positively correlated with lymph node metastasis and poor differentiation in GC, moreover the correlation was more significant among Asian patients, which suggests that DAPK1 methylation was involved in the metastasis of GC in Asian patients." (PMID 28934284, 2017). "There was a significant difference in the methylation level of DAPK1 gene between lymph node metastasis group and nonmetastasis group (40.3 ± 100.5 in the former vs. 12.3 ± 18.5 in the latter, P < 0.05)." (PMID 21639921, 2011). "Similarly, there was a trend toward a higher frequency of DAPK1 methylaton in patients with lymph node metastasis than without metastasis (OR = 5.17, 95% CI = 0.64-42.0)." (PMID 21507233, 2011).
B cell lymphoma (8 papers, 2013 to 2023). "Tumor suppressor activities have been shown for DAPk1 and DAPk2 and they are downregulated in e.g., Hodgkin’s (HL) and B cell lymphoma (CLL), respectively." (PMID 28976934, 2017). "The promoter region of DAPk1 and DAPk2 (members of the DAPk gene family) are reportedly hypermethylated in multiple tumor types with the highest frequency of DAPk methylation detected in B-cell lymphoma." (PMID 28976934, 2017).
glioblastoma (8 papers, 2019 to 2024). The most malignant astrocytic tumor (WHO grade IV). "In summary, models incorporating DAPK1-related parameters offer robust patient stratification for prognostic evaluation and immunological profiling in glioblastoma." (PMID 39926603, 2024). "A DAPK1 inhibitor partially prevented the reprogramming of glioblastoma cells produced by PTBP1 knockdown, indicating the participation of UNC5B-DAPK1 pathway once again." (PMID 35664063, 2022). "An in-depth examination of DAPK1’s specific mechanisms in glioblastoma could elucidate its role in immunotherapy response." (PMID 39926603, 2024). "As a result, DAPK1 may be a potential target for glioblastoma therapy and warrants further investigation." (PMID 35664063, 2022). "In U-251 malignant glioblastoma cells, CUR mediated G2/M cell cycle arrest was explained by the elevation of the protein kinase 1 (DAPK1) level, which suggests that inhibiting DAPK1 via CUR stimulates cell arrest and also causes NF-κB and STAT3 suppression and caspase-3 activation." (PMID 33800000, 2021). "Curcumin was also able to induce G2/M cell cycle arrest by increasing protein kinase 1 (DAPK1) in U-251 malignant glioblastoma cells, which indicates that suppressing DAPK1 by curcumin does not only induce cell arrest but also inhibits STAT3 and NF-κB and activates caspase-3." (PMID 30818786, 2019). "In general, sh-DAPK1 and TC-DAPK 6 suppress DAPK1 catalytic activity, allowing U251 glioblastoma cells to proliferate and then disrupt the reprogramming process." (PMID 35664063, 2022).
multiple myeloma (8 papers, 2010 to 2024). "Safingol synergistically sensitized epigallocatechin-induced apoptotic cell death, and suppressed multiple myeloma cells by preventing protein tyrosine kinase phoshorylation and activation of death-associated protein kinase 1 (DAPK1)." (PMID 32722626, 2020). "Allele-specific DAPK1 methylation patterns were also studied in a cohort of 67 multiple myeloma patients, and all of the methylated multiple myeloma samples heterozygous for the rs13300553 SNP were methylated on both alleles." (PMID 25229255, 2014). "Furthermore, through suppression of RTK phosphorylation and activation of death-associated protein kinase 1, the SphK1 inhibitor safingol synergistically sensitized EGCG-induced proapoptotic cell death and tumor suppression in multiple myeloma cells (DAPK1)." (PMID 38419070, 2024). "To further investigate a potential role of carrying monoallelic methylation of the A-allele in hematologic cancer, we studied 67 samples from patients with multiple myeloma as DAPK1 has previously been shown to undergo methylation mediated silencing in this disease." (PMID 25229255, 2014). "In addition, allelic DAPK1 methylation patterns were studied in a cohort of 67 multiple myeloma patients." (PMID 25229255, 2014). "Moreover, methylation of BM742401 correlated with shorter OS in newly diagnosed myeloma, similar to CDKN2A and DAPK1 methylation, suggesting an adverse impact of BM742401 methylation for OS." (PMID 32855620, 2020). "Moreover, methylation of RNF130/miR-340 correlated with shorter OS in newly diagnosed myeloma, similar to CDKN2A and DAPK1 methylation." (PMID 31064412, 2019).
nasopharyngeal carcinoma (8 papers, 2012 to 2023). A carcinoma arising from the nasopharyngeal epithelium. "Grifolin induces dephosphorylation and up-regulates death-associated protein kinase 1 (DAPK1) in nasopharyngeal carcinoma cells NPCs and HONE1." (PMID 22582152, 2012). "miR-483-5p decreases the radiosensitivity of nasopharyngeal carcinoma cells by targeting DAPK1." (PMID 31471531, 2019).
squamous cell carcinoma (8 papers, 2006 to 2023). A carcinoma arising from squamous epithelial cells. "Methylation of CALCA, CDH1, DAPK1, and EVX2 was more common in squamous cell carcinomas (SCC) compared to adenocarcinomas (ADC)." (PMID 21507233, 2011). "Squamous cell carcinomas revealed frequent promoter methylation, that is in >40% of cases, of CDH13 (nine out of 16: 56.3%), DAPK1 (nine out of 16: 56.3%), MGMT (15 out of 16: 93.8%) and CADM1 (nine out of 16: 56.3%)." (PMID 17971771, 2007).
lymphoma (7 papers, 2002 to 2020). A malignant (clonal) proliferation of B- lymphocytes or T- lymphocytes which involves the lymph nodes, bone marrow and/or extranodal sites. "This was also confirmed in the present study in which Dapk1−/− BMDMs and DAPK1-knockdown Jurkat T lymphoma cells were more resistant than their WT counterparts to FasL- or ER stress-triggered death." (PMID 32366830, 2020).
melanoma (7 papers, 2018 to 2024). A malignant, usually aggressive tumor composed of atypical, neoplastic melanocytes. "In this study, the results showed that hnRNP A2B1 suppressed apoptosis of melanoma stem cells through post-transcriptional regulation of apoptosis-related DAPK1, SYT7, RNF128, EIF3H, TPPP3, and DOCK2 genes." (PMID 33509274, 2021). "In addition, reduced levels of DAPK1 were shown to be associated with reduced sensitivity to BRAF inhibitor therapy, suggesting its possible role in targeted melanoma therapy." (PMID 30240750, 2018). "The in vivo data indicated that hnRNP A2B1 was required for tumorigenesis by affecting the splicing of TPPP3, DOCK2, EIF3H, RNF128, DAPK1, and SYT7, thus suppressing apoptosis of melanoma stem cells." (PMID 33509274, 2021). "Taken together, these findings revealed that hnRNP A2B1 played a positive role in tumorigenesis of melanoma stem cells in vivo by affecting the splicing of TPPP3, DOCK2, EIF3H, RNF128, DAPK1, and SYT7, thus suppressing apoptosis of melanoma stem cells." (PMID 33509274, 2021). "Our findings revealed that the hnRNP A2B1-mediated splicing triggered the upregulation of TPPP3, DOCK2, and EIF3H, and the downregulation of RNF128, DAPK1, and SYT7 in melanoma stem cells, leading to the suppression of apoptosis of cancer stem cells." (PMID 33509274, 2021). "On the other hand, the hnRNP A2B1 overexpression resulted in significant upregulations of TPPP3, EIF3H, and DOCK2 and downregulations of DAPK1, RNF128, and SYT7 in melanoma stem cells." (PMID 33509274, 2021). "Western blot data indicated that the hnRNP A2B1 silencing led to significant downregulations of TPPP3, EIF3H, and DOCK2 and upregulations of DAPK1, RNF128, and SYT7 in melanoma stem cells compared with the control." (PMID 33509274, 2021). "Collectively, it could be concluded that hnRNP A2B1 promoted tumorigenesis of melanoma stem cells via regulating the splicing of the precursor mRNAs of TPPP3, DOCK2, EIF3H, RNF128, DAPK1, and SYT7." (PMID 33509274, 2021). "Northern blot data indicated that TPPP3, DOCK2, and EIF3H were significantly upregulated in melanoma stem cells compared with cancer non-stem cells, while RNF128, DAPK1, and SYT7 were downregulated in melanoma stem cells." (PMID 33509274, 2021).
oral cancer (7 papers, 2013 to 2025). "In our previous work, we aimed to immunohistochemically detect the presence of DAPK-1 in vessels underlying potentially malignant disorders and oral cancer." (PMID 39553125, 2024). "It has previously been shown that the DAPK1 promoter is hyper-methylated in oral cancer cells and the prevalence of DAPK1 methylation in oral cancer ranges from 7 to 68%." (PMID 28251343, 2018). "DAPK-1 constitutes a possible cancer marker, with proven implications in other human cancers, and there isn't any study on its vascular endothelial expression in the oral cavity, particularly in oral cancer and oral potentially malignant diseases." (PMID 39081443, 2024). "Finally, DAPK-1 methylation might function as a trigger for carcinogenesis in oral potentially malignant lesions, receding until higher degrees of dysplasia transition to oral cancer, where methylation is expected to be present." (PMID 40104466, 2025). "The aim of this study was to investigate the immunohistochemical profile of DAPK-1 in oral potentially malignant disorders (OPMD) and oral cancer." (PMID 40104466, 2025). "The relatively milder expression of DAPK-1 in OL means that, between the two disorders, OLP is less likely to progress to oral cancer." (PMID 39553125, 2024).
acute kidney injury (6 papers, 2017 to 2026). Sudden and sustained deterioration of the kidney function characterized by decreased glomerular filtration rate, increased serum creatinine or oliguria. "The role of DAPK1 in kidney injury, particularly in acute kidney injury (AKI) and chronic kidney disease (CKD), has been a subject of extensive research." (PMID 40918124, 2025). "In septic acute kidney injury (AKI), DAPK1 Peli1 phosphorylation promotes RIP1 binding to caspase-8 and ultimately induces tubular apoptosis." (PMID 38179042, 2023). "Under LPS and dual hypoxia stimulation, destabilized Pellino1 (Ser39 phosphorylation and turnover) induced by death-associated protein kinase 1 (DAPK1) leads to the release of TRIF-RIP1 signalosome to recruit caspase-8 and induces tubular damage and cell apoptosis in acute kidney injury (AKI) model." (PMID 35197966, 2022).
breast tumors (6 papers, 2015 to 2024). "We show here that a substantial fraction of human breast tumors exhibits simultaneous DNA methylation‐dependent loss of expression of NTN1 and of DAPK1, a serine threonine kinase known to transduce the netrin‐1 dependence receptor pro‐apoptotic pathway." (PMID 27378792, 2016). "A large fraction of human breast tumors exhibits simultaneous DNA methylation‐dependent loss of expression of NTN1 and of DAPK1, a serine threonine kinase known to transduce the netrin‐1 dependence receptor pro‐apoptotic pathway." (PMID 27378792, 2016). "For example, a considerable number of human breast tumors and lung tumors show concurrent down-regulated expression of DNA methylation-dependent NTN1 and DAPK1." (PMID 32251318, 2020). "In order to study the mechanisms underlying inhibition of netrin‐1/DRs‐mediated apoptosis, which in a fraction of tumors is neither dependent on netrin‐1 upregulation nor DR silencing, we investigated DAPK1 expression and DNA methylation in breast tumors." (PMID 27378792, 2016).
diffuse large B-cell lymphoma (6 papers, 2011 to 2021). "In diffuse large B-cell lymphoma, DAPK1 is a promising prognostic and/or predictive marker of non-germinal central B-cell–like subtype, significantly reducing DFS and OS." (PMID 34315829, 2021).
papillary thyroid cancer (6 papers, 2013 to 2024). "We observed a significant decrease of DAPK1 in advanced-stage papillary thyroid cancer (PTC) tissues and associated disease-free survival (DFS)." (PMID 34831219, 2021). "The current review focuses on the role of DAPK1 in cancer cells, and particularly the role that DAPK1 plays in papillary thyroid carcinoma (PTC) cells during metastasis." (PMID 39057063, 2024). "In papillary thyroid cancer, pituitary tumors, hepatocellular, and esophageal carcinoma DAPK1 promoter hypermethylation was correlated with advanced tumor stages and worse prognosis." (PMID 31772156, 2019).
prostate carcinoma (6 papers, 2011 to 2023). A carcinoma that arises from epithelial cells of the prostate gland. "In prostate carcinoma, a high frequency of alterations in the promoter methylation status of HIC1, SFRP2, and DAPK1 was detected in patients with prostate carcinomas of high Gleason Score (GS)." (PMID 37388742, 2023). "In the other study, DAPK1 overexpression inhibited tumor growth of prostate cancer cells in an in vivo xenograft model." (PMID 34831219, 2021). "Moreover, discovery of the downstream mediators, ASC and DAPK1, provided new potential therapeutic targets for prostate cancer." (PMID 20684002, 2011).
cholangiocarcinoma (5 papers, 2012 to 2021). A carcinoma that arises from the intrahepatic biliary tree (intrahepatic cholangiocarcinoma) or from the junction, or adjacent to the junction, of the right and left hepatic ducts (hilar cholangiocarcinoma). "DAPK1 gene silencing can prevent the autophagy to induce apoptosis by Dihydroartemisinin in cholangiocarcinoma." (PMID 33777735, 2021). "The high expression of DAPK1 in cholangiocarcinoma can reduce autophagy induced by cholangiocarcinoma cells and promote apoptosis of cholangiocarcinoma cells." (PMID 34315829, 2021).
clear cell renal cell carcinoma (5 papers, 2006 to 2023). "In clear-cell renal cell carcinoma (ccRCC), sunitinib-resistant ccRCC cells showed considerably lower death-associated protein kinase 1 (DAPK1) mRNA and protein levels than sunitinib-sensitive ccRCC cells." (PMID 37790807, 2023). "We investigated the prognostic significance of Death-Associated Protein Kinase 1 (DAPK1) and its role in sunitinib resistance in clear cell renal cell carcinoma (ccRCC)." (PMID 33201837, 2020).